BRCA1 (BRCA1 DNA repair associated)
Diseases named in the same sentence as BRCA1 in open-access papers (continued):
Sharing a sentence is not in itself a finding about the gene and the disease.
cancer (continued). "Importantly, individual disruption of the RING or BRCT recruitment pathways were insufficient to entirely abolish BRCA1 foci, shedding light on how BRCA1 mutant cancers utilize hypomorphic proteins, which often lack these domains, to contribute to residual HR activity and PARPi resistance." (PMID 34408138, 2021). "Hence, early identification of germline mutations in BRCA1 and BRCA2 genes may be relevant for management of patients with PrCa and also for preventing future cancers in their relatives." (PMID 34242281, 2021). "Furthermore, the promise of PARPi in the management of BRCA1/2-deficient cancers is tempered by the fact that HR-proficient tumors do not respond to these agents." (PMID 33589588, 2021). "As with the effect of Apex1 targeting, the cancer-associated mutant BRCA1 could not induce the NRF2-dependent antioxidant response." (PMID 34638302, 2021). "To illustrate the flexibility of CanDI to mine context-specific synthetic sick lethal (SSL) genetic relationships, we hypothesized that the genes that modulate response to a PARP1 inhibitor might be enriched for selectively essential proliferation or survival of BRCA1-mutant cancer cells." (PMID 34663427, 2021). "Rare pathogenic variants in the BRCA1 and BRCA2 genes were selected as an exemplar for detailed analysis of clinically actionable variants in the UK Biobank, and BRCA related cancers (breast, ovarian, prostate, and pancreatic) were assessed in participants through use of cancer registry data." (PMID 33589468, 2021). "In addition, pan-cancer studies provide evidence for factors affecting predisposition to different cancer types, highlighting rare germline cancer susceptibility variants that affect tumour suppressor genes including ATM, BRCA1, BRCA2, BRIP1, and PALB24." (PMID 34253785, 2021). "Germline BRCA1/2 mutation carriers (gBMC) face increased cancer risks that are modulated via non-genetic lifestyle factors whose underlying molecular mechanisms are unknown." (PMID 33543354, 2021). "In settings involving an HRR deficiency due to defects in BRCA1 or two or other proteins involved in this pathway, a non-conservative DNA repair processes come into play resulting in DNA alterations that can increase cancer risk." (PMID 34830878, 2021). "Ultimately, we hope to see future discovery of synthetic lethal partners for non-druggable yet incredibly high-risk CPGs, such as BRCA1/2, and to witness such discoveries’ impacts on targeted cancer therapeutics and prevention in a way that is comprehensive of different tumor types." (PMID 34070674, 2021). "When comparing these findings to those of our previous study in women who did not have a BRCA1 mutation, this observation strengthens the evidence suggesting that exposure to low levels of arsenic may have an impact on cancer incidence in women." (PMID 34283078, 2021). "In addition to serving as a biomarker, ATM and BRCA1 are potential targets for anti-cancer therapy." (PMID 34068585, 2021). "Therefore, PARP3 and BRCA1 are synthetic lethal, and targeting the catalytic activity of PARP3 might be a promising therapeutic strategy for BRCA1-associated cancers." (PMID 34976832, 2021).
cancer (continued). "The results of differential gene expression analysis show that in BC and OV cancers, there is a variation of gene expression profiles in patients with somatic or germline BRCA1/BRCA2 mutations, compared to patients without mutations, as well as between mutation types for the same gene." (PMID 33525353, 2021). "Indeed, it has been previously shown that germline BRCA1/2 cancers are less immunologically active, which could be attributed to the compromised immune system because of the mutations." (PMID 33525353, 2021). "However, mutations in the BRCA1/2 gene are “autosomal dominant inheritance,” meaning that not all mutation carriers develop cancer, but only those with this mutation have high cancer susceptibility." (PMID 32356124, 2020). "However, they were not significantly enriched more in BRCA1/2-mutated cancers expressing wild-type POLQ than in other types of cancers." (PMID 32885167, 2020). "Additionally, no specific BRCA1/2-associated cancer type demonstrated a significant association with high GS." (PMID 33351846, 2020). "Although BRCA1 and BRCA2 as double-stranded DNA repair genes preferentially promote tumorigenesis of breast and ovarian epithelial cells, supportive evidence still exists that shows that BRCA1/2 might play a role in the progression or prognosis of other cancer types." (PMID 32879886, 2020). "In addition, BRCA1 is predominantly nuclear in normal mammary epithelial cells, suggesting that the association between BRCA1 and p-ACCA in the cytoplasm regulates ACCA only in cancer cells which have upregulated fatty acid synthesis." (PMID 33212987, 2020). "Response to PARPis in different BRCA1/2-associated cancers varies widely, and BRCA1/2-mutations are not synonymous with HRR deficiency, as other secondary somatic mutations may restore or bypass BRCA function." (PMID 33233320, 2020). "Finally, we applied BRAID analysis to identify a clear pattern of consistently enhanced AKT sensitivity in a subset of cancer cell lines, and a far richer array of PARP inhibitor combination therapies for BRCA1-deficient cancers than would be identified by traditional synergy analysis." (PMID 32198459, 2020). "There are currently clinical trials underway that are investigating the efficacy of PARPi in multiple cancer types, including those without BRCA1/2 mutations, which might have mutations in other HR genes." (PMID 33015624, 2020). "Interestingly, while these studies shown that the inhibition of such targets are linked to the impaired viability of BRCA1-deficient cells in vitro, these types of approaches are not yet established as alternatives for the treatment of BRCA1-related cancers." (PMID 33424604, 2020). "Moreover, PARP1 has been implicated in the protection and stabilization of stalled replication forks due to replication stress—a function that gains extreme importance in BRCA1/2-deficient context and rationalizes once more the use of PARPi in treating BRCA-deficient cancer patients." (PMID 32784607, 2020). "ATR inhibition is lethal with numerous cancer-associated changes, including oncogenic stress (oncogenic RAS mutations, MYC and G1/S-specific cyclin-E1 (CCNE1) overexpression), deficiencies in DNA repair (TTP53, BRCA1/2, partner and localizer of BRCA2 (PALB2) and ATM loss) and other defects." (PMID 32316968, 2020). "However, some women belonging to families with an identified pathogenic variant in BRCA1 or BRCA2 will develop cancer despite testing negative for the family’s pathogenic variants and are often denoted as phenocopies." (PMID 33198123, 2020).
cancer (continued). "Mediators of such cell-nonautonomous mechanism of cancer predisposition could also represent useful biomarkers to facilitate overall evaluation and clinical management of BRCA1 mutation carriers." (PMID 32120796, 2020). "Moreover, we revealed 29 BRCA1/2 mutation carriers (13.9% of patients) in 208 OC patients diagnosed at ≥60 years with no family cancer history, while Morgan and colleagues detected only two (4.3%) BRCA1/2 mutations in 46 sporadic OC patients ≥ 60 years." (PMID 32295079, 2020). "In our patient cohort, refinement of patients with variants of unknown significance reduced the uncertainty of cancer-predisposing syndromes by 64.7% and identified three cases with potential family risk to HBOC due to a likely pathogenic variant BRCA1 p.V1653L (NM_007294.3:c.4957G > T; rs80357261)." (PMID 32486089, 2020). "Loss of PARP1 expression was not tolerated in cancer cells carrying a mutation in the BRCA1 gene." (PMID 32686903, 2020). "A better understanding of the circulating factors mediating cell-nonautonomous effects of the BRCA1 mutation carrier state should also lead to the identification of novel biomarkers of cancer risk predisposition, facilitating evaluation of cancer risk in germline mutation carriers." (PMID 32120796, 2020). "In addition to cancer cells lacking BRCA1/2, many others with HR deficiencies are reliant on alt-EJ for their growth, including those with mutations in RAD51, CHD1, PALB2, and FANCD2." (PMID 32660124, 2020). "However, neoadjuvant systemic therapies should be individualized because tumors with a BRCA-1 mutation are basal, but not all basal cancers express BRCA-1 mutation." (PMID 32245065, 2020). "Thus, the role of BRCA1 upon estrogen challenges exceed the HR mechanism, which is also supported by different mutational processes revealed by distinct patterns of genomic imprints born by BRCA1 and BRCA2-mutated cancers." (PMID 33087072, 2020). "Based on the existing studies, BRCA1/2 mutation carriers should be not be excluded from utilization of fertility treatments, but at the same time take part in a clinical registry to follow up cancer history." (PMID 32719921, 2020). "However, it was less frequent for BRCA1 breast (7%) and ovarian (10%) cancers." (PMID 32481735, 2020). "The false-negative rate was higher in biliary, lung and other cancer types, although these error estimates may not be entirely accurate due to the low number of BRCA1/2 deficient samples in these cancer types." (PMID 33149131, 2020). "However, the results presented here have uncovered an unexpected role for ID4 in the DNA damage response in BLBC, suggesting a similar dichotomy of function to BRCA1, that is, primarily regulating transcription during development whilst predominantly regulating the DNA damage response in cancer." (PMID 32527287, 2020). "Based on recent reports suggesting synergy between epigenome-targeting agents and PARP inhibitors, with HDAC inhibitors inducing a BRCA-ness state, we tested differential growth responses of isogenic cancer cells carrying or not a BRCA1 mutation to epigenome-modifying agents." (PMID 31840082, 2019). "Therefore, even though we report findings of previously undiscovered pathogenic germline variants, particularly in BRCA1 and BRCA2, the potential clinical benefit of PARPi treatment in these drug-resistant patients at advanced stage of cancer remains unclear." (PMID 31263571, 2019). "Our study demonstrates that MCL1 inhibition considerably enhances response of BRCA1-mutated TNBC to the clinical PARPi olaparib and suggests that this combination should be prioritized for clinical evaluation, especially in BRCA1-mutated cancer patients with poor response to PARPi monotherapy." (PMID 30674894, 2019). "Thus, BRCA1 Alu-mediated rearrangements represent an additional mechanism of PARPi/chemo-resistance, and could serve as a predictive biomarker of clinical response in patients with BRCA1 BRCT mutant cancers." (PMID 31827092, 2019).
cancer (continued). "In most patients without the BRCA1 mutation, cancer was located in the right breast." (PMID 31597313, 2019). "Recently our group has demonstrated that exosomes isolated from the sera of cancer patients are able to transfer malignant traits to immortalized cells such as HEK293 (Human Embryonic Kidney cells) and oncosuppressor-mutated cells (OMCs) such as BRCA1-mutated human fibroblasts." (PMID 30787346, 2019). "Indeed, CTSS depletion restored BRCA1 expression and delayed tumor growth in a tumor xenograft model, which was not occurred in both CTSS and BRCA1 double deficiency tumors, suggesting the role of CTSS in cancer cells with intact BRCA1 function." (PMID 30006610, 2019). "Also, women with BRCA1- or BRCA2-associated cancer had an increased frequency of breast stem cells in noncancerous breast tissue, which were identified by expression of the stem and progenitor cell marker ALDH." (PMID 30930946, 2019). "Remarkably, however, a recent study indicated that most somatic BRCA1/2 alterations in non-BRCA associated cancer types may be incidental findings unrelated to tumor pathogenesis, rendering them therapeutically irrelevant." (PMID 31921645, 2019). "In light of the increasing numbers of clinical trials involving HDAC inhibitors in human cancers, our observations strongly suggest that the BRCA1 status and tumor hypoxia should be considered as potentially important clinical parameters that may affect the therapeutic efficacy of HDAC inhibitors." (PMID 31273285, 2019). "While non-malignant cells carrying cancer-predisposing BRCA1 mutations exhibit increased genomic instability, it remains unclear whether BRCA1 haploinsufficiency affects transcription and chromatin dynamics in breast epithelial cells." (PMID 30995943, 2019). "Hormone receptor-positive BC (regardless of the BRCA1/BRCA2 mutation status) is currently considered a cancer with a favorable prognosis, allowing the omission of adjuvant chemotherapy, shorter course of adjuvant hormonal treatment (no longer than five years), and other “de-escalation” approaches." (PMID 31141992, 2019). "However, the benefits might be limited to certain populations, such as patients with a mutation of breast cancer gene 1 (BRCA1), breast cancer gene 2 (BRCA2), or both (BRCA1/2)." (PMID 31795359, 2019). "The germline status of BRCA1/2 in individuals with cancer defines a target population in whom PARP inhibitors seem beneficial, supporting the hypothesis that therapy directed against a genetically defined target has activity regardless of anatomic organ of origin." (PMID 31032221, 2019). "Thus additional factors apart from the status of BRCA1/2 or HR may also contribute to the sensitivity of cancer cells to PARP inhibitors." (PMID 30741937, 2019). "Interestingly, PARPi resistance can be reversed with a small molecule inhibitor P1-B that suppresses the U2 snRNP spliceosome machinery, leading to a silencing of the splicing event responsible for generating BRCA1-∆11q and re-sensitization of cancer cells to PARPi treatment." (PMID 30463359, 2018). "These two variants, BRCA1:c.‐192T>C and BRCA2:c.‐296C>T, were observed in population subgroup controls; notably BRCA1:c.‐192T>C was observed at a frequency of >1%, which is considered stand‐alone evidence against pathogenicity (defined as high risk of cancer) for BRCA1/2 variation." (PMID 30204945, 2018).
cancer (continued). "Applying the criteria for high-risk cancers only which were not confirmed to be BRCA1/2-negative might have decreased the power of detecting associated markers." (PMID 30323354, 2018). "We focused on the cancer’s earliest age of onset in the subject with double heterozygosity and a careful examination of literature revealed that this is in agreement with previous findings and was not unexpected in patients carrying double heterozygosity for BRCA1 and BRCA2 genes." (PMID 29346284, 2018). "However, the target population is not limited to BRCA1/2 mutation carriers, and information about cancer risks is limited and not visually presented." (PMID 29281161, 2018). "These families may have additional genetic variants, which not only may increase the susceptibility of the families’ path_BRCA1/2, but also be capable of causing cancer in the absence of the path_BRCA1/2 variants." (PMID 29371908, 2018). "It has been proposed that these families may have additional genetic variants, which not only may increase the susceptibility of the families’ path_BRCA1/2, but also be capable of causing cancer in the absence of the path_BRCA1/2 demonstrated in the families." (PMID 29371908, 2018). "Furthermore, single gene targeting in vitro in some cases generated not just one but multiple mutational signatures, buttressing previous reports that multiple in vivo cancer-derived signatures could arise from single gene defects such as in BRCA1/BRCA217." (PMID 29717121, 2018). "We also hypothesized that higher levels of DNA methylation within LINE-1 and Alu regions and within the promoter region of the hTERT gene and that lower levels of DNA methylation within the promoter regions of the APC, BRCA1, and RASSF1 genes would be associated with a reduced risk of cancer." (PMID 29953441, 2018). "Wild-type BRCA1, but not cancer-predisposing mutants, possesses the chromatin remodeling ability." (PMID 30558184, 2018). "Prevalence of P/LP BRCA1/2 variants in cohort, proportion of variant carriers not previously ascertained through clinical testing, and personal and family history of relevant cancers among BRCA1/2 variant carriers and noncarriers." (PMID 30646163, 2018). "The non-systematic inclusion of men from BRCA1/2 families in the counselling process may also prevent the opportunity to improve health practices and to transmit cancer risk information to offspring." (PMID 29456621, 2018). "The prevalence of occult carcinomas in BRCA1 carriers is almost 1, 5% if the prophylactic bilateral salpingoophorectomy is performed before the age of 40, while this percentage may be increased to 3, 8% for women who undergo the surgery between 40 and 49 years." (PMID 30340058, 2018). "To ascertain clinical relevance of transcription-related BRCA1 functions, we first used immunofluorescence (IF) staining to compare R-loop intensity in formalin-fixed paraffin-embedded (FFPE), cancer-free breast tissue from BRCA1 mutation-carrying women versus non-carriers." (PMID 28649985, 2017). "Prediction of their possible cancer association is especially difficult in pleiotropic genes such as BRCA1, where disruption of a specific function or domain may not necessarily affect downstream tumor suppression activity." (PMID 28050887, 2017). "Further β-hCG is expressed in BRCA1 deficient cancer cells irrespective of triple negative status." (PMID 28869585, 2017).